MYOC (myocilin)
Diseases named in the same sentence as MYOC in open-access papers (continued):
Sharing a sentence is not in itself a finding about the gene and the disease.
glaucoma (continued). "Therefore, preventive measures targeting mitochondrial protection may delay the onset of glaucoma in individuals carrying the Pro370Leu myocilin mutation." (PMID 19390644, 2009). "The primary mechanism by which the MYOC Y371D mutation causes glaucoma may involve misfolding and intracellular sequestration of the mutant protein within the trabecular meshwork cell, thereby altering cell-mediated processes that control aqueous humor outflow." (PMID 19784393, 2009). "Heterozygous mutations in the myocilin gene (MYOC) cause glaucoma by an unknown mechanism." (PMID 19023451, 2008). "Different mechanisms could contribute to the disease phenotype in myocilin-associated glaucoma." (PMID 19023451, 2008). "Whilst further work is needed, these approaches hold promise for potential gene-targeted therapies for MYOC-related glaucoma to become available in the future." (PMID 41011222, 2025). "The stop-gain variant chr1:171636338 was predicted to increase expression in females and decrease expression in males for the gene MYOC, and had a CADD score of 37 and is likely pathogenic for glaucoma." (PMID 40452186, 2025). "Through literature review, several key glaucoma-related genes were identified, including MYOC, TBK1, COL1A1, COL1A2, FOXC1, LRP2, OPTN, and TEK." (PMID 40808675, 2025). "Mutations in the myocilin gene (MYOC) are the leading genetic cause of primary open angle glaucoma (POAG), the most common glaucoma type." (PMID 41210166, 2025). "Non-viral CRISPR-Cas9 mRNA delivery edits mutant MYOC, alleviates ER stress, and reverses ocular hypertension in myocilin glaucoma, offering a safe, one-time therapeutic strategy beyond viral vectors." (PMID 41210166, 2025). "Myocilin missense mutations comprise the strongest genetic link to open angle glaucoma (OAG), estimated to account for more than 3 million cases of heritable primary open angle glaucoma and more than 150,000 cases of juvenile-onset open angle glaucoma." (PMID 39726989, 2025). "Whilst gene‐specific therapies currently do not exist for glaucoma, some studies have shown promising results to improve the glaucoma phenotype in MYOC mice models using either chemical chaperones (phenylbutyrate) or CRISPR genome editing." (PMID 39929609, 2025). "Here, we demonstrate that the delivery of Cas9 mRNA via a cationic lipid polymer (lipoplex) targets the TM selectively and edits the MYOC gene, thereby rescuing a mouse model of glaucoma." (PMID 41210166, 2025). "Despite these features, the introduction of numerous different single nonsynonymous point mutations in the myocilin OLF domain leads to TM cell death and an accelerated time frame for IOP elevation and glaucoma-associated vision loss." (PMID 39726989, 2025). "Variants in MYOC are usually associated with strong family history, high IOP, variable age of onset, and more severe glaucoma if untreated." (PMID 39929609, 2025). "A single intracameral injection of Cre-mRNA lipoplex resulted in mutant MYOC expression in the TM, leading to glaucoma in a recently developed Cre-inducible mouse model of glaucoma." (PMID 41210166, 2025). "Previous studies have reported that Myocilin (MYOC), a gene known to be associated with glaucoma, functions as a modulator of the Wnt signaling pathway." (PMID 40869377, 2025). "A novel approach to induce mutant MYOC using lipoplex-carrying Cre mRNA has produced robust glaucoma phenotypes in our recently developed Tg.CreMYOCY437H mice." (PMID 41210166, 2025). "The most extensively studied glaucoma gene with high penetrance is MYOC (myocilin), a TM-inducible glucocorticoid response gene." (PMID 39456800, 2024). "We have previously demonstrated that Ad5_crMYOC decreases mutant MYOC in TM and rescues glaucoma in transgenic mice." (PMID 38521856, 2024). "Ser341Pro of the MYOC transmitted from the father was identified in a patient diagnosed with primary open angle glaucoma (POAG) (Case yx9)." (PMID 38785568, 2024).
glaucoma (continued). "Causative variants in CYP1B1 negatively impact its ability to metabolise 17β estradiol resulting in the overexpression of MYOC and can potentially lead to the development of glaucoma." (PMID 38755526, 2024). "This is a validated experimental model of steroid-induced glaucoma, and myocilin upregulation by glucocorticoids is a phenotypic marker of Trabecular Meshwork strains." (PMID 39337505, 2024). "Numerous genes and genetic changes have been described in association with childhood glaucoma, with the most common being CYP1B1, MYOC, and FOXC1." (PMID 38386645, 2024). "Next, we used Sanger sequencing to determine the nucleotide sequence of the coding region of MYOC in glaucoma patients." (PMID 39669598, 2024). "We selected CEP164 for this experiment because of its known localization to centrosomes and a previously reported observation of myocilin, another known glaucoma-related gene in the centrosomes." (PMID 39337513, 2024). "Three genes associated with glaucoma have been identified within specific loci, including myocilin/TIGR (GLC1A), optineurin (GLC1E), and WDR36 (GLC1G)." (PMID 39456800, 2024). "Through linkage analysis, 23 loci and four genes (MYOC/TIGR, CYP1B1, OPTN, and WDR36) had already been associated with glaucoma in the past years." (PMID 38241218, 2024). "Pathogenic variants in TBK1, MYOC, and OPTN are associated with primary open-angle glaucoma (POAG) with severe visual field defects." (PMID 39669598, 2024). "Among these, the most extensively studied glaucoma gene is myocilin (a TM-inducible glucocorticoid response gene)." (PMID 39456800, 2024). "We performed an initial study to identify pathogenic variants in the MYOC and CYP1B1 genes, which were the only fully-described glaucoma-causing genes at that time." (PMID 38241218, 2024). "Glaucoma genetic testing is currently limited to Mendelian genes (e.g. MYOC) which explain less than 5% of adult onset glaucoma." (PMID 37875865, 2023). "Noda and colleagues described the expression of myocilin, the product of the gene MYOC/TIGR that is responsible for the pathogenesis of primary open-angle glaucoma in astrocytes of the optic nerve head." (PMID 37760829, 2023). "Inherited missense mutations in the myocilin (MYOC) gene, within its olfactomedin (OLF) domain, constitute the strongest genetic link to primary open-angle glaucoma via a toxic gain of function, and thus MYOC is an attractive precision-medicine target." (PMID 36579626, 2023). "This latter evidence has challenged the pathological role of myocilin in promoting steroid-induced glaucoma (~40% of cases) after long-term glucocorticoid treatment (e.g., dexamethasone)." (PMID 38152303, 2023). "It is suggested that the proteolytic cleavage degree in linker domain of mutant MYOC is correlated with severity of glaucoma." (PMID 35615698, 2022). "In conclusion, our data demonstrate that MYOC-N450Y induces ER stress, activates autophagy and leads to glaucoma phenotypes in vivo." (PMID 35615698, 2022). "The foundations of our understanding of the role of ER stress in glaucoma were laid in 1997, with the discovery of the myocilin (MYOC) gene." (PMID 35624748, 2022). "Myocilin, a protein expressed in glaucoma, has long been considered a matricellular protein because of its de-adhesive effects on TM cells and interactions with multiple ECM proteins." (PMID 35693935, 2022). "These new antibodies should find broad application in glaucoma and other research areas where myocilin plays a role." (PMID 34384785, 2021). "MYOC locus in the GLC1A codes for myocilin and mutations in this locus is considered as a contributor factor for 3%-5% of adult-onset primary open-angle glaucoma." (PMID 34513615, 2021). "Myocilin is a 55–57 kDa extracellular glycoprotein with an enigmatic function and was identified in 1997 as the first glaucoma gene." (PMID 33573230, 2021).
glaucoma (continued). "Previous studies from our laboratory have shown that topical ocular eye drops of sodium 4-phenylbutyrate (PBA) rescued mouse models of GC or MYOC-induced glaucoma (Tg-MYOCY437H mice)." (PMID 34576258, 2021). "Because of the relationship between myocilin and glaucoma, the eyes were the principal focus of our phenotypic analysis." (PMID 33573230, 2021). "The major component of the myocilin protein is a well-structured olfactomedin (OLF) domain, and more than 90% of glaucoma-related mutations are located in this domain." (PMID 34828408, 2021). "Myocilin is a secreted glycoprotein with a poorly understood biological function and it is mainly known as the first glaucoma gene." (PMID 33573230, 2021). "Myocilin expression is increased upon other glaucoma-relevant stressors such as steroid treatment and mechanical stretching, suggesting broad relevance of myocilin to the TM and ocular pressure homeostasis." (PMID 34384785, 2021). "Trabecular meshwork (TM)-inducible myocilin (the MYOC gene) was the first to be identified and linked to juvenile and primary open-angle glaucoma." (PMID 34828408, 2021). "Regarding association with glaucoma, dominant-inherited single-point mutations in the OLF domain of myocilin lead to its facile aggregation into amyloid-like fibrils, a significant source of conformational heterogeneity." (PMID 34384785, 2021). "Mutations in the myocilin olfactomedin domain (OLF) that lead to aggregation and intracellular sequestration result in hereditary primary open-angle glaucoma." (PMID 34384785, 2021). "Further biophysical studies of the thermostability of those myocilin mutants, together with accurate genomic testing, will provide us with valuable information for glaucoma prevention and treatment." (PMID 34828408, 2021). "While this weak correlation would validate the notion that myocilin protein stability is associated with TM cell death due to ER stress, it may also suggest that other factors, such as environment and genetic background, may also play a role in glaucoma development." (PMID 34828408, 2021). "Deletion of CHOP corrected impaired autophagy, enhanced recognition and degradation of mutant myocilin by autophagy, and reduced glaucoma in Tg-MYOCY437H mice." (PMID 33539326, 2021). "Multiple research data has confirmed the role of MYOC missense mutations in the activation of ER stress and the UPR signaling pathway, indicating their direct correlation with glaucoma pathogenesis." (PMID 33925820, 2021). "Myocilin is a protein with an incompletely understood function, mainly known because of its role in glaucoma." (PMID 33573230, 2021). "We have previously developed a transgenic mouse model of myocilin glaucoma and demonstrated that transgenic mice exhibit glaucoma phenotypes similar to myocilin patients." (PMID 32854767, 2020). "Using rudimentary tissue–culture assays, the physiology and gene expression of primary TM cells was thoroughly studied, leading the identification of the first glaucoma-related gene—myocilin." (PMID 32599818, 2020). "Mutant myocilin is degraded when cellular levels of Grp94 are reduced using siRNA, as well as when Grp94 is inhibited pharmacologically in cells and in the myocilin-glaucoma mouse model." (PMID 31484937, 2019). "As with other protein conformational disorders, working out the role that mutant myocilin plays in glaucoma has had higher priority than identifying the biological function of myocilin in its normal, wild-type state." (PMID 31009450, 2019). "In its normal state, myocilin is secreted at relatively high levels to the TM, and the TM is diseased in most forms of glaucoma." (PMID 31009450, 2019). "Such information should lead to a better understanding of myocilin in normal physiology, as well as the role of myocilin misfolding in normal eye aging, glaucoma, and possibly other scenarios in the body." (PMID 31067323, 2019).
glaucoma (continued). "The Pre-N subdomain appears culpable for the aberrant interaction seen previously between Grp94FL and mutant/misfolded myocilin that forms glaucoma-relevant cytotoxic co-aggregates." (PMID 31484937, 2019). "In the long term, well-characterized antibodies targeting myocilin will enable new insights into its function and involvement in glaucoma pathogenesis." (PMID 31067323, 2019). "Due to its role in glaucoma, myocilin expression has primarily been studied in ocular tissues involved in this disease and its presence in the trabecular meshwork, ciliary body and AH has been well established." (PMID 30557320, 2018). "MYOC is well known for its association with several subtypes of glaucoma including juvenile open-angle glaucoma (JOAG) and primary open-angle glaucoma (POAG)." (PMID 29780638, 2018). "Although more than 15 loci have been identified for glaucoma till date, only five genes have been identified with the causative mutations which include the following: MYOC/TIGR, OPTN, ASB10, WDR36, and EFEMP1." (PMID 28707069, 2018). "To date, more than 15 loci have been identified for glaucoma, and the causative gene has been identified for 5 of these loci: GLC1A (MYOC/TIGR), GLC1E (OPTN), GLC1F (ASB10), GLC1G (WDR36), and GLC1H (EFEMP1)." (PMID 28150229, 2018). "A myocilin (MYOC) mutant mouse glaucoma model demonstrating trabecular meshwork cell death and IOP elevation emphasizes the importance of trabecular meshwork cell function for normal aqueous outflow." (PMID 30534608, 2018). "Approximately 10% of glaucoma cases are the result of genetic variants of myocilin, optineurin or WDR36, and 20% of primary open-angle glaucoma patients are involved in an even wider genetic link." (PMID 30371760, 2018). "As both, FOXC1 and MYOC, are central genes in early-onset glaucoma pathogenesis we examined the interaction between these two genes, by looking at the effect of FOXC1 on exogenous MYOC secretion." (PMID 28575017, 2017). "We found that FOXC1 knockdown, through regulation of RAB3GAP1, RAB3GAP2 and SNAP25, leads to decrease in both intracellular and extracellular levels of MYOC, tying these genes into a common pathway of glaucoma pathogenesis." (PMID 28575017, 2017). "Here, a Grp94-selective inhibitor facilitated mutant myocilin degradation and rescued phenotypes in a transgenic mouse model of hereditary primary open-angle glaucoma." (PMID 29263415, 2017). "Exclusion of pathogenic variations in known glaucoma genes as CYP1B1, MYOC, FOXC1, PITX2 and PAX6 was additionally done per Sanger sequencing and Multiple Ligation-dependent Probe Amplification (MLPA) analysis." (PMID 27484908, 2016). "For example, we recently reported the crystal structure of the best studied OLF domain from myocilin (myoc-OLF), a protein linked to inherited forms of glaucoma in populations throughout the world." (PMID 26121352, 2015). "TGF-β1, TGF-β2 and DEX are principal pathological factors that are involved in the pathogenesis of glaucoma The PHTM cells were characterized by increased myocilin expression after 7 days of DEX (10−7 M) treatment." (PMID 26275042, 2015). "In order to confirm these findings and to rule out that the observed effect is restricted to the nee mouse model, we repeated the experiment using splenocytes obtained from MYOC mice, a distinct IOP-associated genetic glaucoma mouse model." (PMID 26374513, 2015). "Myocilin (MYOC), Optineurin (OPTN), WD repeat domain 36 (WDR36) and CYP1B1 are well-established causative genes for various forms of glaucoma." (PMID 25054348, 2014). "Knowledge of the degradation pathways acting on myocilin can help in design of novel therapeutic strategies for myocilin-related glaucoma." (PMID 24732711, 2014). "The similarity suggests that myocilin-related glaucoma shares common features with neurodegenerative diseases." (PMID 24732711, 2014).
glaucoma (continued). "The most extensively studied member of the olfactomedin protein family is myocilin, which belongs to subfamily III, and is associated with glaucoma." (PMID 25364714, 2014). "Two mutations in consecutive residues of MYOC, p.Val426Phe (family ICO-45) and p.Ala427Thr (ICO-24), previously reported as causing glaucoma, were detected in two index patients." (PMID 23922489, 2013). "The variable phenotype expression of glaucoma, even in families, cannot be explained with a digenic mechanism between MYOC and CYP1B1." (PMID 23922489, 2013). "A better understanding of the level at which myocilin disrupts normal cell physiology will provide a novel therapeutic opportunity for the treatment of glaucoma." (PMID 24367514, 2013). "Further studies are required to determine the scope of receptors with which myocilin interacts, in particular the specific receptor(s) in ocular cells involved in myocilin glaucoma." (PMID 24367514, 2013). "The first glaucoma gene identified, MYOC, was a glaucoma candidate gene because of its glucocorticoid inducibility." (PMID 23836780, 2013). "Particularly important for ocular use, mapracorat demonstrated a decreased activation profile for the glaucoma-related protein myocilin compared with dexamethasone in trabecular meshwork cells." (PMID 23878502, 2013). "This suggests that glaucoma precipitates either due to inadequate levels of secreted MYOC or hampered TM cell function." (PMID 26997785, 2013). "MYOC gene, initially found to be associated with POAG was the first gene found to be implicated with any type of glaucoma." (PMID 26997785, 2013). "Since mutations in myocilin cause glaucoma, two disease-causing point mutations were tested for their impact on l-DOPA-stimulated recruitment of myocilin to the “bound” protein fraction." (PMID 24367514, 2013). "Genome-wide association studies showed that only two identified genes, myocilin (MYOC) and optineurin (OPTN), are well-established glaucoma-causing genes." (PMID 24019741, 2013). "This is the most frequent MYOC mutation reported in Caucasian patients and normally causes mild phenotypes, unlike what was seen in patient II:3 (ICO-4), who had a severe form of glaucoma." (PMID 23922489, 2013). "Contrary to other known genes causing PCG (CYP1B1) or POAG (MYOC, OPTN, and WDR36), one can easily consider a plausible cellular and molecular basis for association between LTBP2 and the glaucoma phenotype." (PMID 23401661, 2013). "Our study on the transcripts altered by overexpression of MYOC mutants in glaucoma-relevant primary human cells provides key insights on the potential mechanisms leading to the development of MYOC-linked glaucoma." (PMID 22615763, 2012). "Our goal in this study was to gain insight into the molecular mechanisms linking MYOC mutants to the development of glaucoma." (PMID 22615763, 2012). "The aim of this study was to characterize a representative sample of the Peruvian population suffering open-angle glaucoma (OAG) with respect to the myocilin gene (MYOC) mutations, glaucoma phenotype, and ancestry for future glaucoma risk assessment." (PMID 22879734, 2012). "A look at the genes representing trabecular meshwork relevant functions and physiological markers of glaucoma by the use of heat maps revealed that most of genes in those lists are affected by overexpression of MYOC mutants." (PMID 22615763, 2012). "Four genes, including trabecular meshwork inducible glucocorticoid response (MYOC), human dioxin-inducible cytochrome P450 (CYP1B1), optineurin (OPTN), and WD repeat domain 36 (WDR36), have been identified as glaucoma-associated genes." (PMID 22876119, 2012). "Myocilin mutants inhibit the proteolytic processing and the extent of inhibition has been correlated with the severity of the glaucoma phenotypes." (PMID 22615763, 2012). "Mutations in CYP1B1 have also been reported in primary open angle glaucoma (POAG) cases and suggested to act as a modifier of the disease along with Myocilin (MYOC)." (PMID 23028769, 2012).